SIK3 (SIK family kinase 3)
Diseases named in the same sentence as SIK3 in open-access papers (continued):
Sharing a sentence is not in itself a finding about the gene and the disease.
cancer (19 papers, 2015 to 2026). A tumor composed of atypical neoplastic, often pleomorphic cells that invade other tissues. "This patient was identified to have a missense VUS with a high score of pathogenic prediction in the ERCC6L2 and SIK3 cancer-related genes in addition to VUS in the SMAD6 CRC-related gene." (PMID 36077770, 2022). "Before evaluating WNK3 and SIK3, we first confirmed that H460 and H2009 cells stably expressing shPD-L1 exhibited increased susceptibility (decreased cancer cell viability) to IL-2 and anti-CD3-activated peripheral blood mononuclear cells (PBMCs)." (PMID 36357569, 2022). "Here, we established a Drosophila model of cancer cachexia using overexpression of Hipk and constitutively active Sik3 in larval epithelial tissue." (PMID 42299622, 2026). "EF-hand domain-containing protein D1 (EFHD1) and salt-inducible kinase 3 (SIK3) have been studied in several cancer types." (PMID 39895792, 2025). "On the other hand, increasing glucose levels activate SIK3/mammalian target of rapamycin (mTOR) activity, which augments cancer cell proliferation and aerobic glycolysis." (PMID 36731029, 2023). "SIK3 plays crucial mediating roles in the three essential cancer signalings: cell proliferation, inflammation, and metastasis, and has been related to anti-inflammatory activity and chronic inflammation." (PMID 33803960, 2021). "As metastasis is a one of the hallmarks of cancer proliferation, we studied the potential effect of SIK3 on the expression of CXCR4 chemokine receptor, an adhesion and tumor metastatic factor." (PMID 28658303, 2017). "To determine the role of SIK3 on high salt and IL-17 synergized proliferative effect on cancer cells, we studied the effect of SIK3 on cell cycle phases following various treatment conditions." (PMID 28658303, 2017). "In line with this literature evidence, we demonstrate specific upregulation of SIK3 following stimulation with high salt on cancer cell lines." (PMID 28658303, 2017). "In conclusion, we report upregulation of SIK3 a novel serine/threonine kinases specifically in the in vitro high salt tumor microenvironment with future application cancer diagnosis and drug therapy." (PMID 28658303, 2017). "Taken together, our data suggests a critical role of SIK3 in mediating three important hallmarks of cancer namely, cell proliferation, inflammation and metastasis." (PMID 28658303, 2017). "Further synchronization of cell cycle in G2 phase along SIK3 knock down significantly abrogated the cell cycle progression following high salt and IL-17 stimulation, suggesting that SIK3 exerts its cancer proliferation effect through release of G1/S arrest." (PMID 28658303, 2017). "Our current studies along with previous observations potential suggest a mTORC2/ SIK3 cascade plays an important role in Warburg metabolism and enhances cancer proliferations." (PMID 28658303, 2017). "Based on these findings, we speculated that EFHD1 may exert anti-cancer effects in CRC by regulating SIK3 expression." (PMID 39895792, 2025). "The expression of SIK3 was predominantly localized to the cytoplasm of cancer cells." (PMID 31762812, 2019). "Unlike the biological functions of SIK1 and SIK2, the functions of SIK3 are unknown, particularly in cancer." (PMID 31762812, 2019).
cancer (continued). "In our current study, using phospho-proteomics approach, we have identified a novel salt specific kinase, salt-inducible Kinase-3 (SIK3), to play a critical role in mediating high salt induced inflammatory signaling responses leading to cancer cell proliferation." (PMID 28658303, 2017). "We further confirm our finding by ELISA-based activity studies of HDAC4, Akt and S6K1 which further confirm that mTORC2 and SIK3 are sequentially activated by IL-17 and high salt, respectively, to potentially induce a synergistic inflammatory and cell proliferation effect in cancer cells." (PMID 28658303, 2017). "To date, there is very limited evidence on the role of SIK3 in cancer metastasis." (PMID 28658303, 2017). "However, the dysfunction of SIK3 has been identified in various types of cancers." (PMID 39895792, 2025). "Although shSIK3 and SIK3 inhibitors decreased PD-L1 levels in cancer cells, a SIK3 inhibitor, YKL-06-062, rendered the cancer cells resistant to the immune cells in the coculture condition." (PMID 36357569, 2022). "SIK3 expression also increases the expression of chemokine CXCL12 and its specific receptor CXCR4 on cancer cells, promoting metastasis." (PMID 31888295, 2019). "The four cancer cell lines MCF7, MDA-MB231, BT-20, and AU565 demonstrated upregulation of SIK3 expression following co-treatment with high salt and IL-17." (PMID 28658303, 2017). "Taken together, these data clearly demonstrate that SIK3 mediates pro-metastatic CXCR4 expression following high salt and IL-17 induction to cancer cells." (PMID 28658303, 2017). "We tested a panel of clinically approved tyrosine kinase inhibitors used for treating various human cancers for their ability to also inhibit SIK2 and SIK3 in vitro." (PMID 25351958, 2015). "BBR not only could directly bind to oncogenes ephrin-B2, SIK3, and LSD1 and inactivated their functions in BC but also modulated the transcription of some cancer-related genes via directly binding to their cis-acting elements." (PMID 36119505, 2022). "While the non-malignant breast cell line MCF10A did not demonstrate SIK3 expression, suggesting SIK3 expression is specific to cancer phenotype." (PMID 28658303, 2017).
tumor (18 papers, 2015 to 2025). "The expression of SIK3 is much higher in normal tissues than in the tumor tissues of patients with CRC." (PMID 39895792, 2025). "Further, reduced tumor progression was noted in mice injected with shRNA-based SIK3 knock-out (SIK3-KO)-MCF-7 cells." (PMID 40563574, 2025). "According to most reported research, SIK1 is considered a tumor suppressor, while SIK2 and SIK3 are often associated with tumor promotion." (PMID 39063214, 2024). "In support of this, SIK1 and SIK3 were shown to control IL-6 production in tumor cells and IL-6 and IL-1β production in Raw264.7 macrophages." (PMID 37140993, 2023). "In non-small cell lung cancer models driven by the KRAS[Gly12Asp] mutation, the tumour suppressive activity of LKB1 has been reported to be dependent on SIK1 and SIK3." (PMID 33861845, 2021). "Loss of Sik1 and Sik3 in the SIK subfamily, resulted in intensified tumor growth in in vivo models of KRAS-driven NSCLC." (PMID 34781949, 2021). "In these studies, lentivirus was used to deliver Cre-recombinase to drive the expression of KRAS[Gly12Asp] whilst simultaneously delivering CRISPR guides to disrupt SIK1 and SIK3 expression, which accelerated tumour growth." (PMID 33861845, 2021). "Authors concluded that SIK1 and SIK3 were highly responsible for STK11 tumor suppressing functions and can therefore be important targets to mediate these pathways for therapeutic reasons." (PMID 34781949, 2021). "Taken together, this study shows that fly Sik2 and Sik3 can promote tumor formation, that proper regulation of Sik2 and Sik3 is required for normal eye development, and that Siks functionally interact with the Notch pathway." (PMID 32542037, 2020). "In this study, we focused on fly homologs of Sik2 and Sik3, their importance for development of the retina, and their involvement in tumor progression." (PMID 32542037, 2020). "Materials and Methods: We collected EOC samples from 204 patients and examined tumor SIK3 expression by immunohistochemistry (IHC) and CA125 expression in tumors and serum." (PMID 31762812, 2019). "The tumor sections of patients were used to detect SIK3 and CA125 expression by immunohistochemistry." (PMID 31762812, 2019). "In 88 advanced-stage serous EOC samples, the percentage of cells positively stained for ABCG2 and SIK3 in the tumor region was scored and analyzed." (PMID 31762812, 2019). "In addition, SIK3 expression was lower in CRC tumor tissues than in normal tissues, and EFHD1 overexpression significantly increased the protein level of SIK3." (PMID 39895792, 2025). "Furthermore, small molecule inhibitor, prostratin, exerted anti-tumor effect in murine models through SIK3 inhibition." (PMID 29861863, 2018). "Furthermore, gelatin zymography analysis has demonstrated that SIK3 induced expression of tumor metastatic CXCR4 through MMP-9 activation." (PMID 28658303, 2017). "Therefore, inhibition of SIK3 can potentially reduce tumor growth and invasiveness." (PMID 36731029, 2023). "Compared to the individual drug, Erianin combined with 5-FU notably inhibited the expression of LKB1, SIK2, SIK3, and PARD3 in mouse tumor tissues." (PMID 39063214, 2024). "Protein and gene expression analyses in patient samples revealed that SIK1, SIK2, SIK3, and PARD3 were all highly expressed in tumor tissues compared to adjacent normal tissues (p < 0.01)." (PMID 39063214, 2024). "IHC and western blot analyses revealed that Erianin inhibited the expression of LKB1, SIK2, SIK3, and PARD3 in a dose-dependent manner in the mouse tumor tissues, and 5-FU also significantly reduced the levels of these proteins." (PMID 39063214, 2024).
tumor (continued). "In contrast to that of SIK3, the expression pattern of CA125, a membrane protein, was typically confined to the surfaces of tumor cells." (PMID 31762812, 2019). "Tumor volume at the end of day 39 in mice injected with high salt passaged MCF-7s cells was 478 ± 79 mm3; while tumor volume in mice injected by SIK3-KO-MCF-7s cells on day 39 was 164 ± 57 mm3 (p < 0.05)." (PMID 29861863, 2018).
metabolic disease (1 paper, 2012). A congenital disorder (due to inherited enzyme abnormality) or acquired (due to failure of a metabolically important organ) disorder resulting from an abnormal metabolic process. "In the present study, profiling the metabolic changes in Sik3−/− mice represents a new start to the study SIK and may also provide novel insights into the metabolic diseases caused by Western diets." (PMID 22662228, 2012).
skeletal dysplasia (1 paper, 2025). Any Mendelian diseases that affects growth and development of the skeleton. "A homozygous mutation in the catalytic domain of SIK3 (Arg187Cys, rs1565460853) impairs SIK3 activity and leads to skeletal dysplasia by altering mTOR activity downstream of the PTH/PTH-related protein signaling during skeletogenesis." (PMID 40384110, 2025). "In 2018, Csukasi and colleagues reported a new skeletal dysplasia caused by a homozygous mutation in the catalytic domain of SIK3 (Arg187Cys) and observed decreased activity of mTORC1 and mTORC2 due to accumulation of DEPTOR, a negative regulator of both mTOR complexes." (PMID 40384110, 2025).
SIK3 also shares sentences with these, for which no sentence is quoted: hypertriglyceridemia (4 papers); cholelithiasis (2); Sepsis (2); adenomyosis (1); Arthritis (1); autoimmune disease (1); chronic eosinophilic leukemia (1); ciliopathy (1); colorectal cancer (1); endometriosis (1); endotoxemia (1); gastric adenocarcinoma (1); gastric cancer (1); Hyperglycemia (1); Hyperinsulinemia (1); Insulin resistance (1); lymph node metastasis (1); metastatic tumors (1); muscular dystrophy (1); neurodegenerative disease (1); Shock (1); spondyloepiphyseal dysplasia (1).